LYVE1 (lymphatic vessel endothelial hyaluronan receptor 1)
Diseases named in the same sentence as LYVE1 in open-access papers (continued):
Sharing a sentence is not in itself a finding about the gene and the disease.
tumor (continued). "We discovered the following new and important results: blood vessels are mainly located in the middle of the tumor, whereas LYVE1-immunopositive cells (lymph endothelial cells) and immune cells are mostly found in the outer section of the tumor." (PMID 37237550, 2023). "Quantification and statistical analysis by Inform software confirmed that the LYVE1+ area was increased in tumor sites of claudin-3−/− mice indicating the presence of more lymphatic vessels existed." (PMID 36261482, 2022). "As a role of Lyve-1 during leukocyte adhesion to lymphatic EC is described, the subtypes of infiltrating immune cells in tumor-free and metastasized Ctrl and Lyve-1-KO livers were analyzed in detail by flow cytometry." (PMID 36496412, 2022). "Tumor-free Lyve-1-KO livers showed increased numbers of CD4+ T cells (P = 0.0094), CD8+ T cells (P = 0.0449), regulatory T cells (Treg) (P = 0.0389) and eosinophils (P = 0.0139) compared to Ctrl livers, whereas other immune cell subtypes remained unchanged." (PMID 36496412, 2022). "M2 macrophages injected into heterotopically implanted 4T1 murine breast cancer tumors promoted primary tumor growth and lung metastases, and this phenotype was associated with increased expression of VEGF-A, VEGF-C, LYVE-1, HIF-1alpha, and CD31 in vivo." (PMID 35216243, 2022). "This can be taken advantage of therapeutically, as administration of a monoclonal anti-Lyve-1 antibody strongly decreased tumor formation and lymphatic metastasis of breast cancer in a mouse model." (PMID 36496412, 2022). "The potential influence of Lyve-1 on the sinusoidal immunological microenvironment and the fact that LYVE-1 had been described to be able to mediate tumor cell adhesion in vitro, prompted us to study models of hepatic metastasis in Lyve-1-KO mice." (PMID 36496412, 2022). "In line with our data, BM-derived myeloid cells activated by IL-4/IL-13 upregulated lymphatic-specific markers Lyve-1 and stabilin-1 in several tumor models." (PMID 35442077, 2022). "We further found that αSMA, CD31 expression level and tumor mass were significantly pairwise positively correlated, while LYVE1 expression was negatively correlated with tumor mass." (PMID 34983554, 2022). "After slicing the tumor, LYVE-1 immunohistochemistry showed that the enrichment of lymphatic vessels in the exosome-injected tumor was higher than that in the control group." (PMID 36230535, 2022). "Coinjection of pol-TAMs and tumor cells resulted in larger tumor sizes, higher AKT activity and higher Ki67, CD31, and LYVE-1 expression in tumor tissues." (PMID 35962191, 2022). "We did not observe any changes in the gene expression of lymphatic vessel marker Lyve1 in tumor RNA upon propranolol treatment in any of the three models tested." (PMID 35017664, 2022). "LYVE-1 staining showed less lymphatic vascular structure in the tumor site in the sh-FASN group, providing evidence that FASN contributes to LNM in CC." (PMID 35597782, 2022). "IL-4, which shares its pathway with IL-13, is known to induce Lyve-1 and other LEC markers in tumor-recruited CD11b+ cells, whereas deficiency in IL-10 receptor (IL-10R) caused impaired lymphatic formation due to decreased generation of M2 macrophages." (PMID 35442077, 2022). "KYSE30 cells cotransplanting with activated CAFs significantly enhanced tumor volume, increased the expression of proliferative biomarker‐Ki67, lymphangiogenic biomarker‐LYVE‐1, and microvessel biomarker‐CD31, compared with KYSE30 tumors alone." (PMID 34459125, 2021). "Quantification of LYVE-1 positive areas in MCF-7/GFP primary tumor tissues demonstrated that the primary tumor lymphatic vessel density in the recombinant Hsp90α protein group increased by two times compared with that in the control group." (PMID 34299365, 2021).
tumor (continued). "The expression of the tumor markers in both models was similar, with an increase in the mRNA levels of Ly6d, Afp, Gpc3, Birc5, and Lyve1 being higher in DEN-treated WT mice compared to MUP-uPA, while that of Cd44 was comparable in both models." (PMID 34439245, 2021). "Tumor lymphoangiogenesis was evaluated in these samples by Lymphatic Vessel Endothelial Receptor 1 (LYVE-1) immunostaining." (PMID 34948239, 2021). "Of note, LYVE‐1 bears a high degree of specificity for lymphatic vessels, and it has been an essential component of many important studies on tumour-induced lymphangiogenesis." (PMID 33674563, 2021). "The LM describes a process whereby tumor cells form CK+/lymphatic vessel endothelial hyaluronic acid receptor 1 (LYVE-1)+ mosaic endothelial-like vessels in cancer tissues and in vitro." (PMID 35048009, 2021). "CHR-6494 has been reported to inhibit tumor-associated angiogenesis; hence, we examined tumor-associated vasculogenesis by staining MDA-MB-231 tumors for CD31 and LYVE-1." (PMID 33852630, 2021). "Although F4/80+Lyve-1+ cells were found at low levels within the tumor parenchyma, these cells were found to be enriched within the peri-tumoral stroma." (PMID 32479261, 2020). "The microvessel density (CD31) and lymphatic vessel (LYVE1) density in tumor tissues decreased significantly." (PMID 32983976, 2020). "One week later, we found that GFP+ tumor cells overlapped with LYVE-1+ MLV structures, suggesting that the GFP+ cells invade MLVs." (PMID 32094452, 2020). "In our eight mRNAsi based signature, high expression of RGS16, LYVE1, hnRNPC, ANP32A, and AIMP1 are correlated with a high risk of death as these genes focus in promoting cell proliferation and tumor progression, similar to stem cells." (PMID 33329703, 2020). "The number of lymphatic vessels was also increased in the tumor lymph nodes of Ibtk+/-Eμ-myc compared to Ibtk+/+Eμ-myc mice, as stained with the lymphatic vessel marker LYVE-1." (PMID 32019112, 2020). "The nestin+ cells were distributed among LYVE‐1+ lymphatic endothelial cells, and many LYVE‐1+ nestin+ tumor cells were identified." (PMID 31960509, 2020). "In tumour tissues, we also found reduced lymphatic vessel formation by detecting the expression of the lymphatic marker LYVE-1." (PMID 31892990, 2020). "We then investigated the changes of MLVs in mice bearing GL261 or B16 tumors using LYVE-1 immunostaining and found significant lymphatic remodeling, especially in the dorsal meninges 1 week after tumor cell injection." (PMID 32094452, 2020). "Quantification of LYVE-1+ vessel diameter and area confirmed lymphangiogenesis in the meninges of tumor-bearing mice." (PMID 32094452, 2020). "On tumor sections obtained on D5 post tumor inoculation (2 days after tamoxifen delivery), the large majority of Prox1+ cells co-localized with Lyve1 and Podoplanin expressing lymphatics in the periphery of the tumor." (PMID 30604758, 2019). "To study β4 expression in vivo, we used primary 4T1.2 tumor sections stained with Lyve1-Cy3 and β4 integrin-Cy5." (PMID 31091437, 2019). "Immunofluorescence and ISH in human CSCC tissues also demonstrated that high miR-221-3p levels in tumor were accompanied by reduced VASH1 expression in LYVE1-positive lymphatic vessels and enhanced PLVD." (PMID 30254211, 2019). "Next, we performed staining for CD31 and LYVE-1 to study tumor invasion into the vein and lymph vessels, respectively, because invasion of PDAC cells was inhibited by CXCR2 inhibitor in vitro." (PMID 30659170, 2019). "Among these genes, PLP2 was upregulated and positively associated poorer survival, whereas LYVE1, FABP4, TGFBR3, and FXYD6 were downregulated and identified as tumor suppressor genes." (PMID 31803141, 2019). "In accordance, CD31 staining of primary tumor sections revealed only minimal difference between the two groups, whereas Lyve1 and Podoplanin staining of lymphatics was significantly increased in the absence of Rbpj." (PMID 30604758, 2019).
tumor (continued). "The results showed that the content of LVD in tumour tissues was positively correlated with the expression of LYVE‐1/VEGFR‐3 and VEGF‐C29." (PMID 30648805, 2019). "We have previously measured lymphangiogenesis markers VEGFC and LYVE-1 expression in these tumour samples." (PMID 31277414, 2019). "Although in tumor tissues only LYVE-1 expression is significantly upregulated, there is a notable tendency of higher expression of nearly all markers after loss of CYLD, which supports the role of CYLD in regulating lymph angiogenesis." (PMID 31591386, 2019). "LYVE-1-positive vessel-like structures were found in control tumours, and hyperplastic lymphatic vessels were observed in the tumour periphery." (PMID 29752441, 2018). "We confirmed the effects of 3AOA on tumor-related lymphangiogenesis, the essential course of lymph node metastasis through immunohistochemical analysis of primary tumor and sentinel lymph node tissues using the lymphatic vessel marker LYVE-1 antibody." (PMID 29976150, 2018). "We investigated the effects of 3AOA on VEGF-A-induced lymphangiogenesis in primary tumor and sentinel lymph nodes via immunohistochemical analysis using anti-LYVE-1 antibody." (PMID 29976150, 2018). "In vivo studies showed that SRC-1 knockdown restricted tumor growth, reduced the numbers of LYVE-1-positive lymphatic vessels, and decreased the levels of VEGFC in tumor tissues." (PMID 29717026, 2018). "Here, the average photon flux, which strongly correlates with tumor volume, was significantly increased in tumors developing in Lyve-1-/- mice already seven days after tumor cell injection compared to tumors in wild-type mice." (PMID 29262593, 2017). "Comparing with para-cancerous tissues, tumor tissues had significantly lower expression levels of LYVE–1 (P < 0.001) and VEGFR–3 (P = 0.013) and higher levels of Podoplanin (P = 0.016) and Prox–1 (P = 0.078)." (PMID 29162097, 2017). "In this study, we analyzed the possible implication of LMW-HA binding to soluble Lyve-1 derived from TAMs on tumor growth." (PMID 29262593, 2017). "We found that hypoxia effectively activates PlGF expression in lymphatic endothelial cells as well as in LYVE1 positive tumor vessels." (PMID 28427198, 2017). "A higher tumor end weight accompanied by increased tumor cell proliferation was observed in Lyve-1-/- mice pointing towards a tumor growth inhibiting effect of this molecule." (PMID 29262593, 2017). "Using LYVE-1 staining to identify LVs within the tumor mass and in the tumor periphery, we found increased PDL1 staining within the lymphatic endothelium of tumor-associated LVs, compared to LVs in the back skin of naive C57BL/6 mice." (PMID 28217128, 2017). "Immunohistochemical analyses were performed on the ear sponge sections to investigate the distribution of lymphatic vessels (LYVE-1+, blue staining) and tumor cells (tyrosinase+, pink staining) at 2 and 4 weeks after sponge implantation." (PMID 28128294, 2017). "Monitoring of B16F10 LUC tumors in vivo by luminescence measurement further sustained the tumor-inhibiting role of LYVE-1." (PMID 29262593, 2017). "We found that BDNF knockdown inhibited tumor growth and the expression of the lymphatic vessels marker LYVE-1." (PMID 28771226, 2017). "Lymphatic vessels and B16F10Luc+ tumor cells in LNs resected from mice after 2 and 4 weeks of sponge implantation were detected by double immunolabeling for LYVE-1 and tyrosinase, respectively." (PMID 28128294, 2017). "Knockdown of VEGFC blocked stress-induced LYVE-1+ LVD in primary tumours, demonstrating a key role for tumour cell VEGFC in stress-induced lymphatic remodelling." (PMID 26925549, 2016). "Next, we stained the tumor and peritumoral area with a LYVE-1 antibody to assess the lymphatic vessel density in Chy mice." (PMID 27329584, 2016).
tumor (continued). "Chronic stress significantly increased tumour LYVE-1 staining compared with control tumour-bearing mice, demonstrating that stress-induced SNS signalling can increase the lymphatic network within primary tumours." (PMID 26925549, 2016). "Inhibition of COX2 activity blocked the effect of stress on tumour LYVE-1+ LVD and prevented metastasis to lymph node and distant organs, demonstrating a functional consequence of limiting lymphatic remodelling." (PMID 26925549, 2016). "To identify NSCLC cell lines that induce lymphangiogenesis, we stained a panel of 13 NSCLC tumor xenograft samples from previous animal experiments with antibodies against LYVE-1 and podoplanin." (PMID 26950548, 2016). "While weaken expression of CK20, LYVE-1 and D2-40 protein products, with little brown tan vessels with rebirth tumor cells, invaded and destroyed microvessel profile among apoptotic tumor cells." (PMID 26187792, 2015). "YL529 remarkably decreased the amount of lymphangiogenesis in tumor tissues at 150 mg/kg for 14 days in VEGF-D-LL/2 tumor syngeneic model, as indicated by the LYVE-1 staining (34.71 % higher than the vehicle group in VEGF-D-LL/2 muscle model)." (PMID 26187637, 2015). "LYVE-1-positive lymph vascular structures in the tumor peripheries were flattened and cluttered compared to those of the control." (PMID 26656588, 2015). "An examination of tissue sections of lung metastases by immuno fluorescent staining using an antibody against Lyve-1 confirmed a significant reduction of tumor lymphangiogenesis in the null mice compared to controls." (PMID 25635825, 2015). "Double staining of Lyve-1/CD146 allowed us to distinguish between Lyve-1(-)CD146high tumor blood vessels in HCC and Lyve-1(+)CD146low tissue in peritumoral liver." (PMID 25238265, 2014). "In this study, we investigated the patterns of tumor lymphangiogenesis using monoclonal D2-40 and LYVE-1 antibody, as a predictive marker for disease-free survival in patients with CLM." (PMID 24963215, 2014). "Quantitative analyses of CD31-positive and LYVE-1-positive vessels showed significant reductions in the tumor microvascular and lymphatic vessel densities in anakinra-treated tumors versus untreated tumors (*p<0.05, **p<0.01)." (PMID 24924428, 2014). "Lymphatic staining in ME180 tumor sections was minimal (% positive LYVE-1 was 2.7±0.6%) and limited to the periphery." (PMID 24312530, 2013). "In summary, high-low cell surface HA content of tumor cells through the interaction with LYVE-1 leads to adhesion differences." (PMID 23717428, 2013). "In the peritumoral area the mean LYVE-1-stained LVD was higher than that within the tumor, 6.7 within the field of view, and the density difference between the compartments was statistically significant (Wilcoxon test: Z = 4.86, P = 0.000001)." (PMID 23238856, 2013). "HA on tumor cells mediates their adhesion through the lymphatic endothelial cell HA receptor LYVE-1." (PMID 23717428, 2013). "In this study, the biological role of the interaction between LYVE-1 and tumor cell surface HA in cancer cell adhesion was investigated." (PMID 23717428, 2013). "IL-7 was shown to increase proliferation, migration, and tube formation of endothelial cells in vitro and the growth of LYVE-1+ vessels in tumor-containing matrigel plugs in vivo." (PMID 22946011, 2012). "Although the numbers of the CD45+CD11b+LYVE-1+ cells seemed to be similar in the vicinity of both tumor types, their shape and arrangement were strikingly different." (PMID 23251384, 2012). "On average there was also a significant increase in Ki67 staining in the epithelial component of the tumor and LYVE1 in both components, however this is variable from one model to another." (PMID 24213469, 2012). "We used these tumor tissues (10 control and 10 periostin-overexpressing tumors) to count the numbers of lymphatic vessels expressing LYVE-1, which was specifically observed in lymph vessels in both control and periostin-overexpressing tumors." (PMID 22952986, 2012).
tumor (continued). "This phenomenon was reduced by enzyme digestion treatment of HS-578T cell surface with bacterial Streptomyces hyaluronidase prior to adhesion experiment, suggesting that LYVE-1 enhances tumor cell adhesion through interaction with hyaluronan." (PMID 22400115, 2012). "To quantify the relative abundance of mouse lymphatics within the human tumor transplants we took advantage of the mouse lymphatic endothelial marker LYVE-1 at protein and mRNA levels." (PMID 22545097, 2012). "Expression of Lyve-1, considered another M2-macrophage related gene, and a gene enriched in tumour infiltrating TIE-2 expressing monocytes (TEMs), was also confirmed by confocal fluorescence microscopy." (PMID 22590615, 2012). "CDL depletion of CD11b+/LYVE-1+ TAMs in a model of ovarian cancer inhibited tumor-induced lymphangiogenesis by 50–75% (p < 0.05)." (PMID 22946011, 2012). "During the analysis of tumor angiogenesis we performed immunostaining using anti-LYVE-1 antibody in order to distinguish between blood vessels (LYVE-1−) and lymphatic vessels (LYVE-1+)." (PMID 23251384, 2012). "Conversely, LNs adjacent and contralateral to tumor-bearing SLNs showed a remarkable increase in LYVE-1-positive sinuses." (PMID 23031500, 2012). "The increased expression of CD31 and lymphatic vessel endothelial hyaluronan receptor-1 in tumor tissues indicates that tumor angiogenesis and lymphangiogenesis were increased in mice co-injected with M2-Mφs." (PMID 22616919, 2012). "The lymphatic vessels in the tumor were detected by immunohistochemistry using the antibody specific to lymphatic vessels, LYVE-1." (PMID 22295235, 2011). "In the 94 LYVE1+ samples, the mean density at the tumor periphery (P-LVD) was 20.30 ± 4.23 vessels/mm2." (PMID 20374665, 2010). "As a result, we confirmed that mouse podoplanin had a staining pattern similar to that of LYVE-1, indicating that the tumor cell nests were circumscribed with lymphatic endothelial cells." (PMID 21034514, 2010). "LYVE-1+ cells were predominantly found in the peripheral regions of tumor nests; staining was weak in intratumoral regions." (PMID 20374665, 2010). "Through Lyve-1 immunolabeling on tumor sections, quantification performed by computerized image analysis led to the determination of 3 different parameters." (PMID 20300183, 2010). "The area and perimeter of LYVE-1-positive lymphatic vessels in viable tumor tissue were significantly lower in EBC1-P-derived tumors than in EBC1-V-derived tumors." (PMID 21034514, 2010). "The method primarily used here is an objective lymphatic density counted from cross sections of LYVE-1 stained lymphatic vessels per mm2 of section in a 350 μm (one high powered field) border around the tumour." (PMID 20478045, 2010). "These lymphatic vessels were mostly distributed in the stromal tissue surrounding the tumor, and tumor cells were observed in some LYVE-1 positive lymphatic vessels." (PMID 19589137, 2009). "The analysis of the distribution of lymphatic vessels showed that lymphatic vessels stained for m-LYVE-1 were located mainly in tumor periphery." (PMID 19821979, 2009). "Immunofluorescence co-staining for F4/80 and the hyualuronan receptor LYVE-1 identified LYVE-1+ macrophages in the tumor periphery with relatively large size compared to intra-tumoral macrophages (data not shown)." (PMID 19759906, 2009). "Lymphatic vessel endothelial hyaluronan receptor-1 (LYVE-1), a marker for lymphatic endothelium, provides powerful tools for studying tumor lymphangiogenesis." (PMID 19232130, 2009). "Using LYVE-1 and podoplanin staining, we identified LVs in all included MM specimens, both within the tumour itself and in the adjacent tissue." (PMID 19628489, 2009).